BRAF (B-Raf proto-oncogene, serine/threonine kinase)
Diseases named in the same sentence as BRAF in open-access papers (continued):
Sharing a sentence is not in itself a finding about the gene and the disease.
tumor (continued). "Forty-four patients who underwent BRAF V600 testing showed a reduction in median OS from 32.1 months (95% CI 19.7–44.5 months) for BRAF wild-type tumours versus 17.2 months (95% CI 1.0–33.4) for BRAF mutant tumours (p = 0.109)." (PMID 36400886, 2023). "Nevertheless, AI has shown that benign urothelium more closely resembles BRAF mutation negative rather than positive tumours, as benign regions were labelled as such in the present study." (PMID 37570213, 2023). "More importantly, dabrafenib (Dab), a v-raf murine sarcoma viral oncogene homolog B1 (BRAF) inhibitor is a drug capable of slowing tumor growth, and its combination with miR-200c turned out to enhance cancer cells’ sensitivity to such medicine by inhibiting the expression of PD-L1." (PMID 37576994, 2023). "BRAF (Z-score=5.546, p<0.001) and PNPLA5 (Z-score=5.546, p<0.001), a gene closely associated with lipid metabolism, were the only two genes implicated in tumor pathogenesis." (PMID 37795451, 2023). "Most BA/CMPT cases have been reported from Japan and other Asian countries and may involve genetic mutations of BRAF, EGFR, KRAS, HRAS, and ALK; thus, the tumor is viewed as an oncological disease." (PMID 39517003, 2023). "Data currently available reveal that miR-100-5p and miR-125b-5p can promote tumor cell proliferation and invasion, at the same time being related to survival time as they can negatively affect patient response to treatment with BRAF inhibitors such as vemurafenib." (PMID 37047539, 2023). "The RAS and BRAF status as well as the sidedness of the primary tumor could also have an impact on the efficacy of induction chemotherapy combined with antibody therapy and are important to include in the therapy decision made by the MDT." (PMID 37296862, 2023). "Aberrant activation of serine/threonine kinases caused by oncogenic BRAF mutation could constitutively activate the MAPK signaling pathway and drive tumor proliferation and antiapoptotic behavior." (PMID 36912150, 2023). "For example, identifying BRAF p.V600E, along with the detection of a mildly and minimally atypical glial proliferation without eosinophilic granular bodies and Rosenthal fibers (RFs), enables categorizing the tumor as a “low-grade diffuse glioma”." (PMID 37397394, 2023). "In addition, more importance was placed on all molecular markers (MSI, KRAS and BRAF) and tumour markers (CEA, CA19.9, CA125) but to a lesser magnitude (i.e. < 10% difference from general cohort responses)." (PMID 37020095, 2023). "In a recent meta-analysis, BRAF mutations were associated with histological subtype and tumor site but not with patient age or sex." (PMID 37649946, 2023). "However, both SLC2A1 (FDR < 0.01) and SLC2A3 (FDR < 0.001) genes—associated with higher glucose uptake and oncogenic growth —are markedly overexpressed in BRAF- (vs RAS)-like tumours." (PMID 37198319, 2023). "BRAF mutation was reported to exist in 35–70% of PTCs, and one mutation called BRAF V600E has been shown to correlate with aggressive characteristics of PTC, including ETE, advanced tumor stage at presentation, CLNM and DM." (PMID 36676734, 2023). "The limitations of the study are the lack of molecular analyses of the tumours such as BRAF or TERT mutations, as these analyses were not routinely performed during the study period and not included in the Swedish national guidelines." (PMID 37099203, 2023). "In the case of wild-type BRAF or non BRAF p.V600E mutation, BRAFi lead to a paradoxical increase in ERK signaling by facilitating the formation of RAF dimers, especially B-RAF-C-RAF, able to accelerate tumor growth in vivo." (PMID 36831610, 2023). "In addition, NLRP3 inflammasome activation by nigericin induced pyroptotic cell death on BRAF V600 inhibitor‐resistant CM tumor cells." (PMID 36707938, 2023). "In LGG, differences in myeloid cells have been observed based on the BRAF-status of the tumor." (PMID 37901250, 2023).
tumor (continued). "Moreover, tunlametinib also showed potent anti-tumor effect in the BRAF/KRAS wild type xenograft model mice." (PMID 37808191, 2023). "BRAF plays a role in the growth, proliferation, invasion, and metastasis of tumor cells." (PMID 36704723, 2023). "Given the contribution of the NF-κB signaling in TC tumor progression, identifying NF-κB upstream activators might prove to have some therapeutic interest for BRAF-advanced PTCs." (PMID 37973791, 2023). "Oncogenic BRAF mutations cause constitutive activation of the BRAF protein, which in turn leads to constitutive downstream activation of the MAPK pathway (MEK1/2 and ERK1/2) contributing to tumor growth." (PMID 37761808, 2023). "The treatment recommendation for wild-type RAS and BRAF tumors is based on primary tumor location." (PMID 37133732, 2023). "The survival trend of PTC patients was analyzed according to the presence or absence of BRAF V600E mutation in tumor tissue." (PMID 37547301, 2023). "To test whether more optimal and complete inhibition of the BRAF/MAPK pathway might enhance the degree of immune gene induction across all tumor models, including those from patients with PFS < 6 months, we utilized a combination of BRAFi and ERKi." (PMID 36702949, 2023). "In addition, we found that the patients with tumours with mutations in PIK3CA, BRAF, CDH1, and NRAS exhibit better survival outcomes than those without mutations in these genes." (PMID 37550388, 2023). "No significant results or trends were found when comparing the tumor stage, the presence or absence of ulcerations, the BRAF mutation status, or the clinical course with the depth of AE or the TEG." (PMID 38201430, 2023). "Different from KRAS and BRAF (V600E) mutation, none of the clinical characteristics, such as age, gender, tumor sites, histological type, differentiation, TNM stage, lymphovascular invasion, and perineural invasion, was associated with NRAS mutation." (PMID 36862900, 2023). "In addition, a complete genetic analysis of the tumour revealed not only the presence of CHEK2 and VHL mutations, but also the presence of deletions in exon 1 of BRAF-1 and PTEN11, genes involved in tumour development by LOF." (PMID 37843608, 2023). "Tumor histology was PTC in 73.2%, including infiltrative follicular variant PTC—tumors with BRAF p.V600E-like molecular profile according to current classification, encapsulated follicular variant PTC in 7.3%, FTC in 13.4%, and oncocytic thyroid carcinoma of follicular cells (OCC) in 6.1%." (PMID 37879236, 2023). "Moreover, our results indicate that the interaction between TCF12 and the BRAF pathway is crucial in mediating the tumor’s response to BRAF-targeted therapy." (PMID 37760480, 2023). "We observed that the enhanced antitumor activity associated with the BRAF/VEGF targeting did not correlate with an increased inhibition of tumor angiogenesis." (PMID 37183363, 2023). "To further confirm the predictive performance of the IRRS, we also compared the C-index values for the IRRS with those for tumor stage, tumor mutation burden (TMB), and driver mutations (BRAF, NF1, and RAS); the results showed that the IRRS had the best predictive effect with respect to prognosis." (PMID 36875110, 2023). "Indeed, BRAF-targeted chemotherapy in patients with papillary CP resulted in a dramatic reduction in tumor volume and cessation of tumor recurrences." (PMID 37174978, 2023). "However, Notch1 and Notch2 can delay tumor development and inhibit their growth once BRAF-induced tumors are initiated in Pten-null mice." (PMID 36672468, 2023). "When comparing the mean size of PCR BRAF-positive UC with their negative counterpart, it was apparent that mutated tumours were approximately twice as big in our validation set (mean BRAF mutation-positive: 16 mm2 versus mean BRAF negative: 9 mm2; p > 0.1)." (PMID 37570213, 2023).
tumor (continued). "Thus, we injected recombinant IL-5 into PK5L1940 and BRAF tumor-bearing mice at biologically relevant concentrations of the amount present in tumors receiving Th2 cells." (PMID 36376448, 2023). "The therapeutic landscape for this tumor has broadened with the development of BRAF inhibitor." (PMID 36844955, 2022). "The gold dashed line represents the patients with KRAS and BRAF wild-type (double wt) tumours." (PMID 34887523, 2022). "cfDNA mutated BRAF was found in 11.6% of cases and was usually consistent with the somatic status, with only one positive case not revealing the mutation on tumor tissue." (PMID 36358788, 2022). "In addition, genetic analysis of cultured cells using next-generation sequencing demonstrated that, concerning BRAF, this population harbored the primary tumour-specific molecular signatures." (PMID 35820816, 2022). "WES identified KRAS, BRAF, and NRAS mutations in a total of 27 tumours (93%)." (PMID 35715628, 2022). "Furthermore, the assessment of the immune profile of BRAF-MT tumors can be helpful to better understand tumor biology and the different clinical outcomes of BRAF-MT CRC." (PMID 35625987, 2022). "BRAF mutations confer stronger activation of ERK signaling, whereas RAS mutations provide oncogenic potential by constitutively activating other signaling pathways that are also related to tumor development." (PMID 36056964, 2022). "Proliferation assessed at 24 h post treatment using ki67 staining also showed a trend to a decrease in all groups but never reached significance, suggesting that additional mechanisms account for tumor growth delay in response to BRAF/MEK inhibition in YUMM1.7 xenografts." (PMID 35327519, 2022). "For chromosome 18q11.2‐q12 no‐loss patients with RAS (KRAS and NRAS)/BRAF wildtype tumors and left‐sided location of the primary tumor, anti‐EGFR in the first‐line is a viable alternative, now recommended solely beyond the first‐line." (PMID 35489024, 2022). "Notably, around 60% of BRAF-mut CRCs also are MSI-H, a condition associated with a higher proportion of tumor infiltrating lymphocytes present in the tumor." (PMID 35582524, 2022). "Totally, enhancing the AK2-BRAF interaction in tumor cells, such as inducing energy deprivation, might provide one strategy to combat BRAF dysfunction." (PMID 35585049, 2022). "Notably, despite an intermediate BRAF score of the BRAFG469A-mutated tumor, the BRAFT599dup-mutated tumor lay at the forefront of the cohort." (PMID 36344509, 2022). "The presence of a BRAF mutation indicates a sporadic MSI tumor and virtually excludes the diagnosis of Lynch syndrome." (PMID 36530921, 2022). "Finally, a correlation between ctDNA levels and metabolic tumour burden was only observed in treatment naïve patients but not at the time of progression in a subgroup of patients failing BRAF inhibition (N = 15)." (PMID 34373567, 2022). "No distinction was found when differentiating tumor subtype (luminal or basal), immune score (score 1-5 from lowest non-T-cell inflamed to highest T-cell inflamed), the presence of the BRAF mutation, or tumor grade (tumor grades 2-4 included in this study)." (PMID 36072391, 2022). "Location-specific differences in the proximal colon might also point to a role of molecular tumor subtypes, such as microsatellite instability (MSI-high) and BRAF mutation." (PMID 35642982, 2022). "Relevant to pediatric LGGs, like NF1-PA and BRAF-driven PAs, the derivative tumor cells undergo oncogene-induced senescence and display a senescence-associated secretory phenotype (SASP) in vitro unless provided with fibroblast conditioned medium and ROCK inhibition or senolytic inhibitors." (PMID 35986378, 2022). "Furthermore, a significant increase in alpha-ketoglutarate, a tumor metabolite, supported the activities of histone lysine demethylases and favored the emergence of dedifferentiated BRAF inhibitor-resistant subpopulations." (PMID 36686803, 2022).
tumor (continued). "Taken together, whether the next-generation BRAF inhibitors perform better and exhibit broader anti-tumor responses than the first-generation inhibitors need further clinical evaluation." (PMID 35966590, 2022). "The BRAF protein was uniformly expressed along the full length of the epithelial lining, as well as in the odontogenic epithelium islets scattered throughout the tumor capsule." (PMID 35468886, 2022). "In addition, genes including BRAF, DCTN1 and RAD51B were among the 20 tumour-related genes that were found to be mutated only in the PTCa and PTCb patients." (PMID 36686473, 2022). "tested the tumor suppression effect of BRAF/MEK inhibitors in CM cell-lines, suggesting that targeted therapy may be useful for patients with CM." (PMID 36059617, 2022). "HPSE knockdown impeded tumor proliferation of BRAF V600E-mutant CRC cells in vitro and in vivo." (PMID 36130926, 2022). "The increased tumor growth in xenograft mice (BRAF mutated) fed with a high-fat diet was not due to differences in the quantity of the food intake." (PMID 35681673, 2022). "DDR signaling might therefore influence both cancer and stromal cells during tumor adaptation to BRAF inhibition." (PMID 34957688, 2022). "BRAF V600E status was similarly assessed in some resected tumour specimens via IHC." (PMID 35884509, 2022). "Preclinical and translational data suggested that BRAF inhibitors (BRAFi) may modulate the tumor microenvironment (TME)." (PMID 36505793, 2022). "Pre-clinical studies show that BRAFi increase the expression of the IFNAR1 receptor on BRAF-mutant tumor cells, potentiating the activity of IFN, and a phase I study combining IFN with vemurafenib plus cobimetinib demonstrated the safety of this triple therapy in the clinic." (PMID 35513054, 2022). "Therefore, since OIS is one of the earliest tumor suppressor mechanisms that is triggered in response to activation of the MEK–ERK pathway by oncogenic mutations in KRAS or BRAF, founder cells have to first overcome OIS for tumor initiation to occur." (PMID 35975243, 2022). "Regorafenib is an oral tyrosine kinase inhibitor that blocks multiple protein kinase activities, including proteins involved in the regulation of oncogenesis (KIT, RET, RAF-1 and BRAF), tumour microenvironment (PDGFR and FGFR) and tumour angiogenesis (VEGFR1, 2 and 3 and TIE-2)." (PMID 35326702, 2022). "The KEYNOTE-006 trial demonstrated a shorter OS in patients with the BRAF V600 mutation in the tumor, compared to patients without this mutation (median OS 13.9 vs. 28.1 months, HR = 0.73, p = 0.0048)." (PMID 35406444, 2022). "In a mouse model of colorectal carcinogenesis in vivo, BRAF V600E mutations in intestinal stem cells promote differentiation and require inactivation of SMAD4 or of intestinal differentiation transcription factor CDX2 for efficient tumor formation." (PMID 36079062, 2022). "Already, clinical trials testing the efficacy of MET inhibitors in METΔexon14-presenting tumours have identified amplification and/or activating mutations in the KRAS or BRAF genes (as well as activating mutations in the PI3K-AKT pathway) to be a common form of acquired resistance." (PMID 35326531, 2022). "Genomic DNA sequencing revealed 2 pairs of bilateral tumors harboring the same BRAF V600E mutation, while the remaining pair of bilateral PTC had different genetic mutations, with BRAF V600E mutation in the right tumor and RET/FARP1 fusion in the left tumor." (PMID 35515000, 2022). "RAS (and BRAF) mutations confer more aggressive tumor biology and are negative prognostic factors in particular in MSS mCRC." (PMID 36230751, 2022). "Observations from preclinical trials suggest that treatment with BRAF/MEK inhibitors may enhance susceptibility towards CPI therapy and thus improve long-term tumor control." (PMID 35565212, 2022).
tumor (continued). "Furthermore, 2′-OMe-modified siBRAF-Mut1_2′-OMe and siBRAF-Mut2_2′-OMe exhibited strong suppression activities on Mut BRAF mRNA in both in vitro and in vivo xenograft tumor models." (PMID 35804932, 2022). "The correlation between CNV, BRAF and tumor size with LN metastasis of PTC." (PMID 36313748, 2022). "HER2, EGFR, BRAF) are overexpressed in a fraction of tumor samples where their inhibition may show efficacy." (PMID 35433463, 2022). "Therefore, if IGH-BCL2 translocation, MYD88 L265P mutation, and BRAF V600E mutation were also detected and the results were combined with the model, the overall predictive sensitivity could increase to 0.88, and was markedly improved in samples with low tumor cell content." (PMID 34802044, 2022). "Systemic targeted treatments were delivered in three HER-negative cases, one within a clinical trial (olaparib followed by palbociclib), two owed to the evidence of actionable tumor mutations (1 tipifarnib for HRAS mutation, 1 dabrafenib and trametinib for BRAF mutation)." (PMID 36733354, 2022). "Exact primary tumor location is associated with various aspects of disease spread; in particular, involved organs appear to depend on the primary tumor location—even in context with a molecular selection of rather favorable RAS/BRAF wild-type disease." (PMID 35158793, 2022). "Moreover, combined inhibition of BRAF and CSF-1R, which recruits M2-polarized macrophages in a tumor, resulted in superior antitumor responses." (PMID 36246599, 2022). "A positive BRAF V600E IHC is most often strong and diffuse throughout the tumor cells." (PMID 35328303, 2022). "First of all, studies have shown that NRAS upregulation is another resistance mechanism of BRAF inhibitors and NRAS upregulation may promote the dimerization of RAF, which will cause insensitivity of ERK signaling to drugs, leading to tumor drug resistance." (PMID 35912223, 2022). "We next assessed our hypothesis that AK2 negatively regulates the BRAF activity in growing tumor cells." (PMID 35585049, 2022). "And the inhibition of BRAF can restore tumor immune recognition." (PMID 36531226, 2022). "Treatment for the recurrent tumor included stereotactic radiotherapy with a dose of 25 Gy in 5 daily fractions prescribed to the 80% isodose line, followed by combination targeted therapy with BRAF/MEK inhibitors (Dabrafenib, Trametinib)." (PMID 35198980, 2022). "The BRAF status was assessed with both methods independently of the percentage of tumor cells." (PMID 35328303, 2022). "However, the majority of patients demonstrated tumour progression within 12 months, indicating that the development of resistance also occurs following treatment with combination BRAF/MEK inhibitor therapy, as seen in other tumour types." (PMID 36582791, 2022). "Tumor biology and drug sensitivity change with the site of the KRAS and BRAF mutations." (PMID 35280113, 2022). "The discrepancy of cytology and BRAF mutation may be due to FNAB bias, which is common in biopsy, especially when the tumor is small." (PMID 35392249, 2022). "The abnormal expression of TEAD could modulate several cancer-associated genes, including MYC, KRAS, NF2, BRAF and LKB1, which had crucial roles in the regulation of tumor immunity." (PMID 35077390, 2022). "BRAF and RAS mutations are mutually exclusive and either mutation is capable of sustaining thyroid tumorigenesis; however, the initial driver mutation confers very different tumor characteristics." (PMID 36056964, 2022). "Several targeted therapies have been approved for the treatment of NSCLC harboring certain genetic variations in EGFR, ALK, ROS1, or BRAF and it is required to determine the existence of those genetic variations in tumor before targeted therapies are given to patients." (PMID 35061839, 2022).